IL6 (interleukin 6)
Diseases named in the same sentence as IL6 in open-access papers (continued):
Sharing a sentence is not in itself a finding about the gene and the disease.
tendinopathy (continued). "Even though various cytokines have been discussed in the research field of tendon inflammation, IL-1β, TNFα, IL-6, and IL-10 are considered in various studies as the key cytokines in tendon diseases, as reported in a systematic review." (PMID 33803624, 2021). "A systematic review of cytokines in tendon disease reported that the expression of IL-1β, IL-6, and TNF-α in animal tendon injury models tended to increase from the early phase of tendon healing." (PMID 34090401, 2021). "Recent analysis of tendinopathy biopsies showed a distinct inflammatory infiltrate in the initial phase of tendinopathy with a high content of pro-inflammatory factors such as IL-6, TNF-α and IL-17." (PMID 32443833, 2020). "In contrast, to prevent tendinopathy the high production of IL-17 by PBMCs is limited, especially when IL-6 and IL-10 production is up-regulated." (PMID 33233549, 2020). "The role of IL-6 in tendon pathologies has been confirmed by several studies, and it is considered one of the evidences of inflammation involvement in tendinopathy." (PMID 31885616, 2019). "Whilst genetic variants in IL1β (rs1143627 and rs16944) have been implicated to an increase in IL1β gene expression, interleukin-6 (IL6) was found to be linked to tenocyte apoptosis, which is a characteristic of tendinopathy." (PMID 28523640, 2017). "In fact, various inflammatory mediators like TNF-alpha, IL-6, IL-15, IL-18 have been shown to play a role especially in wound healing after injury and in early stages of tendinopathy." (PMID 22480275, 2012). "Nevertheless, the action of IL-6 in tendinopathy is complex." (PMID 36543895, 2023). "In animal models of tendon injury, IL-6 gene and protein expression was increased from two hours to four weeks following the intervention, further supporting its role in the pathogenesis of tendon disease." (PMID 34863223, 2021). "IL-6 was the only cytokine involved in human tendon disease and elevated in tendon tears." (PMID 34090401, 2021). "Also, core‐resident “tenophage” or “tenoclast” populations have recently been gaining more attention as potential role players in early tendinopathy, especially in combination with increased expression of Tnf‐α, Il‐6, Mmp‐3, and Mmp‐9." (PMID 34494401, 2021). "Given the wide role of IL6, there is much interest in its role in tendinopathy and tendon healing." (PMID 34350166, 2021). "While this likely represents a critical step in normal tendon healing, it is suggested that extended and excessive IL6 signaling may causally exacerbate tendinopathy in non-sheathed tendons." (PMID 40023978, 2025). "While this likely represents a critical step in normal tendon healing, we propose that extended and excessive IL-6 signaling may causally exacerbate tendinopathy in non-sheathed tendons." (PMID 39918402, 2025). "However, the issue as to whether local injections of IL-6 in tendinopathy patients may be beneficial to the healing process of a damaged tendon is still unknown." (PMID 22480275, 2012). "qPCR analysis indicated elevated mRNA levels of TNF-α, IL-6, and MMP3 in the tendinopathy group, indicating the presence of inflammation in tendinopathic tissues." (PMID 39442875, 2025). "In this work, we screen cell signaling pathways in human tendinopathies and find positively enriched IL-6/JAK/STAT signaling alongside signatures of cell populations typically activated by IL-6 in other tissues." (PMID 39918402, 2025). "The current study found high IL-6 levels produced by the LEE-derived cells, possibly related to the development and progression of this condition, as it is a cytokine involved in tendinopathy in humans." (PMID 35168647, 2022). "Inflammatory mediators (IL-1β, IL-6 and TNF-α) have been reported to be highly expressed in tendon diseases and accelerate the progression of tendinopathy." (PMID 35458235, 2022).
tendinopathy (continued). "An inflammatory infiltrate with a high content of pro-inflammatory cytokines such as IL-6, TNF-α, and IL-17 has been identified in tendon biopsies during the initial phase of the tendinopathy process." (PMID 34575523, 2021). "Inflammation-related genes (MIF, IL-18, IL-6, and TNF) are up-regulated when signs of tendinopathy are moderate, and an inflammatory cellular infiltrate composed of macrophages and mast cells has been observed." (PMID 32977533, 2020). "Together, these data suggest that injections of PRP at the site of tendinopathy could stimulate the production of collagen by tenocytes to accelerate tendon healing and could inhibit inflammation, limiting the release of pro-inflammatory IL-6 and increasing the production of IL-10." (PMID 32977533, 2020). "However, as IL6 has been shown to have both pro- and anti-inflammatory functions, it could play a role in either tendon adaptation or the development of tendinopathy." (PMID 22092479, 2013). "The IL-17A-induced expression of downstream inflammatory effectors IL-6, CXCL1 and MMP3 was completely inhibited by secukinumab, suggesting that IL-17A alone and in concert with TNF-α may promote inflammation in tendinopathy." (PMID 39988349, 2025). "In Achilles tendons with collagenase-induced tendinopathy, NMN increased the mRNA expression of SIRT1 and SIRT6, as well as SOD activity; while suppressing protein expression of NOX1 and NOX4, and mRNA expression of IL6." (PMID 35287653, 2022). "In vitro and in vivo studies by Yamaura and colleagues showed that NMN has antioxidant effects against tendinopathy and promotes the expression of SIRT 1 and SIRT 6, known for their anti-aging and anti-inflammatory roles, while reducing the expression of NOX1, NOX4, Il-6, and ROS." (PMID 38247510, 2024). "However, in combination with TNF-α, all three IL-17 cytokines induce similar levels of IL6 and MMP3 mRNA expression, which could make not only IL-17A, but also IL-17F and IL-17AF interesting treatment targets in tendinopathy." (PMID 35004653, 2021). "Incubation of tendon-derived stromal cells from both healthy volunteers and patients with tendinopathy in SPM including 15-epi-LXA4 or MaR1 induced further release of proresolving mediators and counter regulated the expression of pro-inflammatory molecules including PGE2, IL-6, STAT-1 and PDPN." (PMID 28887458, 2017). "As hypercellularity has often been described as a symptom of tendinopathy, this may be indicative of a negative IL6 effect in tendon." (PMID 22092479, 2013). "Furthermore, the molecular docking results presented the stable and high-affinity binding of NGR1 to TNF-α, IL-6, MMP3, MMP9, and MMP13, indicating that NGR1 may exert its therapeutic effects on tendinopathy by modulating inflammatory responses and cellular and extracellular matrix metabolism." (PMID 40697661, 2025). "Furthermore, not all patients suffering from tendinopathy present with signs of inflammation such as increased IL6 levels, and suppression of inflammation in those patients may not be warranted." (PMID 35329992, 2022). "In vitro, stimulation of tenocytes with TNFα results in increased expression of adhesion proteins and inflammatory cytokines (IL6, IL8), that may add to the inflammatory milieu in tendinopathy, independent of immune cells." (PMID 34350166, 2021).
enteritis (38 papers, 2018 to 2025). Inflammation of the small intestine. "Our findings demonstrate that D-CONGA-Q7 significantly reduces the levels of pro-inflammatory cytokines TNF-α, IL-6, and IL-18, effectively alleviating small intestinal inflammation in a mouse model of enteritis induced by K88 (ETEC) exposure." (PMID 40136483, 2025). "After treatment with IL-6R Ab to block the function of IL-6, the symptoms of enteritis obviously reduced base on the H&E staining of intestine tissue." (PMID 40005679, 2025). "As a conclusion, IL-6 and IFN-γ caused apoptosis of IECs by activating caspase 3, resulting in the enteritis phenotype." (PMID 40005679, 2025). "Periplanetasin-4, a peptide derived from P. americana, ameliorated the severe inflammatory responses in the Toxin A-induced mouse enteritis model, rescuing villous disruption and interleukin-6 production." (PMID 40264666, 2025). "Here, we showed that pro-inflammatory cytokines, especially IL-6, play a very important role in the enteritis phenotype induced by Lp pulmonary infection." (PMID 40005679, 2025). "During enteritis, significant infiltration of inflammation‐associated factors such as TNF‐α, IL‐1β, and IL‐6 causes damage to intestinal epithelial cells, triggering an increase in intestinal permeability." (PMID 40661137, 2025). "The results showed that PUN and CEF significantly down-regulated the expressions of TNF-α and IL-6 proteins in the serum and intestinal wall of mice with enteritis, alleviating the destruction of intestinal wall barrier proteins by inflammatory factors." (PMID 37246319, 2024). "In this experiment, the levels of TNF-α, IL-1β, IL-6, and IL-10 in the mouse colon were measured using ELISA kits to assess the impact of different treatments on inflammatory factors in murine enteritis." (PMID 39697653, 2024). "Compared with WT enteritis mice, Gpr43-/- enteritis mice showed higher expression of IL-6 and IL-22 and more tissue damage." (PMID 39741950, 2024). "Previous studies have shown that probiotics can significantly reduce the levels of IL-1β and IL-6 and increase the level of the anti-inflammatory cytokine IL-10 in the serum of mice with enteritis, thereby alleviating intestinal inflammation." (PMID 37817260, 2023). "At present, it is known that TNF-α, IL-1β, and IL-6 are known to be closely related to the progression of enteritis." (PMID 36076306, 2022). "During the occurrence of enteritis, the up-regulation of pro-inflammatory cytokines (including IL-6 and TNF-α) acts as a protective inflammatory response and leads to inflammation response through the down-regulation of anti-inflammatory cytokines (including IL-10)." (PMID 40564253, 2025). "Next, we investigated the role of IL-6 in the enteritis phenotype." (PMID 40005679, 2025). "High percentage of dietary SBM could induce enteritis in L. crocea, showing increased proinflammatory cytokine production (IL-1β, IL-6, and TNF-α) and decreased anti-inflammatory cytokine expression (IL-4/13a, IL-4/13b, and TGF-β)." (PMID 40688731, 2025). "Table highlighted the diagnostic importance of estimated pro-inflammatory cytokines and APPs, indicating their sensitivities as biomarkers for sheep enteritis, particularly emphasizing IL-1α, IL-6, TNF-α, and Hp due to their highest specificities, LRs, PPVs, and accuracy rates." (PMID 39394128, 2024). "The cytokines TNF-α, IL-1β, and IL-6 represent critical pro-inflammatory substances of enteritis." (PMID 38998101, 2024). "Additionally, IL-6 and IL-1β are important proinflammatory factors in enteritis that exert pleiotropic effects by participating in immune defense, nerve cell function, and hematopoietic function." (PMID 38346819, 2024).
enteritis (continued). "In addition, to assess IBD-like enteritis, IL-6 in the serum was measured by ELISA and was highly detected in the acute and chronic enteritis models but not in the control group or food allergy model." (PMID 36922861, 2023). "Co‐culture with intraperitoneal macrophages from mice with DSS‐induced enteritis significantly increased the levels of inflammatory factors (IL‐6, IL‐11, IL‐22, TNF‐α) in colonic epithelial cells compared to macrophages from healthy mice, whereas GW4868 eliminated this difference." (PMID 33569850, 2021). "The levels of IL-1β (p < 0.0001), IL-6 (p < 0.01), and TNF-α (p < 0.0001) in the serum of mice in the enteritis model group were significantly elevated compared with the CON group, indicating that DSS can trigger systemic inflammatory responses in mice." (PMID 40238292, 2025). "IL-6, IL-1β, and TNF-α are considered biomarkers of inflammation and are positively correlated with the severity of enteritis." (PMID 41007944, 2025). "This experiment used ELISA, PCR, and WB to detect the expressions of PUN and the core targets of bacterial enteritis, i.e., TNF and IL-6, through network pharmacology." (PMID 37246319, 2024). "Fraxetin was reported to mitigate the levels of IL-1β, IL-6, TNF-α and prostaglandin E2, improve the content of superoxide dismutase (SOD) and IL-10 in rats with enteritis." (PMID 37161415, 2023). "The present study found that treatment of SCP-Se NPs more effectively reduced LPS-induced elevation of IL-1β, IL-6, and TNF-α relative to SCP, closely correlated with its anti-enteritis effects." (PMID 36899787, 2023). "After 24 hours of induction of LPS, enteritis cells could secrete higher inflammatory factors TNF-α, IL-6 and IL-1β." (PMID 40948782, 2025). "Furthermore, IL-10 levels were much lower in enteritis mice than in the normal group, while TNF-α, IL-1β, and IL-6 levels were dramatically enhanced after DSS administration." (PMID 37375702, 2023). "In the present study, TS1 also reduced the SE-induced increase in the expression of pro-inflammatory cytokines (IL-1β, IL-6, TNF-α, IL-4, MCP-1) in the intestine and serum, which is consistent with previous findings and observations of lipopolysaccharide-induced enteritis in vitro." (PMID 36759839, 2023). "Levels of the inflammatory factors IL-6 and TNF-α were significantly increased in the colon tissue of mice in the DSS group (P < 0.05) compared with those in control mice, which was suggestive of enteritis." (PMID 34901119, 2021).
hematoma (38 papers, 2014 to 2026). A hematoma is a collection of blood from a vascular structure into an extravascular space. "In recent years, it has been confirmed that the levels of inflammatory factors (such as interleukin-6 and tumor necrosis factor-α) in plasma and dynamic perfusion parameters on MRI are associated with hematoma evolution." (PMID 41137278, 2025). "This is based on our previous findings that mast cell-deficient mice have reduced IL-6 levels in both, the circulation and the hematoma after fracture." (PMID 40368371, 2025). "Increased serum levels of IL-6 and IL-10 were detected in intraparenchymal hemorrhage, and higher admission IL-6 levels were associated with unfavorable 90-day functional outcomes and hematoma and perihematomal edema volumes." (PMID 36439158, 2022). "Based on these findings, it is reasonable to hypothesize that IL-6 levels may be associated with hematoma volume, explaining why IL-6 levels are higher in SICH patients with poorer outcomes compared to those with better outcomes." (PMID 39970158, 2025). "In both blood and hematoma fluid, inflammatory cytokines such as tumor necrosis factor (TNF)-α, interleukin (IL)-6 and IL-10 raise, and the anti-inflammatory activities in the hematoma may play a role in the risk of a recurrence of CSDH." (PMID 32328124, 2020). "Results from the two exploratory factor analysis models indicated a different underlying cytokine pattern in venous blood compared with hematoma fluid samples, which seemed especially so for the pro-inflammatory cytokines IL-6 and TNF-α and the anti-inflammatory cytokines IL-4 and IL-13." (PMID 24587250, 2014). "On the other hand, increased IL‐6 levels had been associated with early hematoma growth in humans, and, accordingly, the reduction in this systemic inflammatory marker observed after CM352 treatment may be the result of the diminished bleeding but also a consequence of MMP inhibition." (PMID 28572282, 2017). "Syk potentially mediates Th2-polarized cytokine secretion (Il-6/Il-10), Cd36 enhances hematoma resolution via Il-10/Stat3 signalling and Cd74 synergizes with MIF to amplify inflammatory cascades." (PMID 40623122, 2025). "In SDH rats, vitamin D treatment significantly decreased TNF-α, IL-6, and IL-8 concentrations in the hematoma and meninges." (PMID 41099766, 2025). "The concentrations of cytokine IL6/IL8/IL10/VEGF in the hematoma fluid of the observation and control groups were significantly higher than those in venous blood (P < .001)." (PMID 38914867, 2024). "Analysis of the hematoma fluid collected intraoperatively revealed that the concentrations of IL6/8/10 and VEGF were abnormally increased, indicating that CSDH was a local inflammatory and angiogenic disease." (PMID 38914867, 2024). "The serum IL-6 level was positively correlated with the relative expression of IL-6 in the fracture end hematoma samples; the correlation coefficient was 142.928, and the regression was statistically significant (P < 0.05)." (PMID 37038178, 2023). "Inflammatory markers in hematoma fluid, including IL-6 and IL-8, were shown to predict CSDH recurrence." (PMID 35207175, 2022). "Then, the levels of IL-6, IL-8 and IL-10 in the capsule of the hematoma were further measured to evaluate the inflammatory response." (PMID 34813498, 2021). "Classic IL-6 signaling was shown to be involved in efficient neutrophil recruitment to the fracture hematoma and to direct endochondral ossification during bone regeneration." (PMID 30013010, 2018). "Another study has found that patients with high concentrations of anti-inflammatory cytokine IL-10 also had high values for IL-6 and CXCL8, in addition to a tendency to be associated with a separated or layer type of hematoma." (PMID 29107999, 2017).